CD44 (CD44 molecule (IN blood group))
Diseases named in the same sentence as CD44 in open-access papers (continued):
Sharing a sentence is not in itself a finding about the gene and the disease.
tumor (continued). "In a subsequent study, same authors detected CD45- CD90+ CD44+ CTCs in 68.3% of enrolled HCC patients, demonstrating a significant correlation with tumor size, TNM stage and, more relevantly, with post-hepatectomy recurrence and survival." (PMID 27738343, 2017). "A reduction in CD44 and LGR5 expression suggested that the drug had an effect on tumour cells with stem characteristics." (PMID 29167573, 2017). "Spheroids obtained for CSC isolation were characterized for the expression of tumor-specific CSC markers CD44+ / CD24−/low for breast CSCs, and CD133+/CD44+ for prostate and ovarian CSCs, by using flow cytometry." (PMID 28536422, 2017). "Having verified that CD133+ cancer cells are CSCs, we examined expression of TF and/or CD44 on CD133+ CSCs isolated from the human cancer lines, tumor xenografts and patients' tumor tissues to identify new biomarkers for CSCs." (PMID 27903969, 2017). "To date, the evidence for CD44 as a specific CCSC marker remains insufficient, although it is widely used as a general CSC marker in many tumours." (PMID 27343550, 2017). "Our studies also demonstrate that afatinib decreases the expression of CSC markers, including CD44 and Oct3/4 in SCC1 and SCC10B cells, and that it reduced the colony- and tumor sphere-forming capability of CSCs." (PMID 28423495, 2017). "In these patients, CD44+CD24- cells were present mainly in solid (96.4% of cases), alveolar (91.6%), trabecular (75.0%), tubular (57.9%), and discrete groups of tumor cells (33.3%)." (PMID 28977854, 2017). "CD44 is mainly expressed by the mesenchymal subtype of GBM cells and seems to exert a crucial role in tumor initiation and progression." (PMID 29348889, 2017). "Consistent with an in vitro study, our immunofluorescence analysis on the tumour sections of EGCG and PDE3 inhibitor-injected mice demonstrated that the combination regimen also suppressed both FOXO3 and CD44 expression." (PMID 28507327, 2017). "The authors identified CD45- CD90+ CTCs in 91% of samples and demonstrated that this cell population expressed key stem-like genes including Bmi1, CD44, Oct4, Notch1, Wnt3a, Stat3, and HIF-1a compared to CD90+ tumor-tissue cells." (PMID 27738343, 2017). "A tumour metastasis PCR array showed that the expressions of many genes (ECADHERIN, NME4, SYK, CD44 and IL1B) were changed in NPC cells with HOPX overexpression." (PMID 28146149, 2017). "All this suggests a role for WFCD2 in rebuilding the tumor microenvironment by regulating the expression of MMP2 and CD44." (PMID 28679402, 2017). "The muscle invasive tumour, however, showed a basal subtype (higher expression of CDH3, CD44, KRT5 and KRT6A) and likewise high aggressiveness (higher expression of KPNA2, BIRC5, CDC25B, COL4A1, and MSN)." (PMID 28916750, 2017). "MU028 (CD44+) and MU035 (CD133+) formed the most aggressive tumors with all mice succumbing to tumours within the 6-month experimental window." (PMID 28241049, 2017). "Many studies have demonstrated cell populations expressing high levels of specific markers such as ALDH, CD44, CD166, CD133, etc. are enhanced for a multitude of tumor phenotypes, with tumorigenicity and drug resistance being clinically the most important." (PMID 28737489, 2017). "Although CD44+/CD24− cells are the most abundant sub-population of cells in certain tumors, in many cases, they constitute only 3–5% of total tumor cells." (PMID 28092266, 2017). "The expression of CD44+/CD24−/low and ALDH1+ has been revealed in the axillary lymph node metastases of breast cancer." (PMID 29062075, 2017).
tumor (continued). "Immunohistochemistry analysis was conducted to assess the protein abundance of DACH1, CD44, Myc, Sox2, Fibronectin, Vimentin, EGFR, Ki-67 in nude mice xenograft tumor tissues with overexpression of DACH1 and the GFP controls." (PMID 28659634, 2017). "Recently, it has been shown that CD74 and CD44 promote actin polymerization via RHOA-mediated CFL1 phosphorylation; it is thought that this interaction contributes to tumour metastasis." (PMID 29190904, 2017). "Cell surface proteins such as CD44 and CD24 are used to distinguish cancer stem cells (CSCs) from the bulk-tumor population." (PMID 27521216, 2016). "Under these anchorage-independent conditions, bedaquiline diminished the CD44+/CD24− low cancer cell population, which are believed to be the tumor-initiating cells." (PMID 27344270, 2016). "CSCs can be defined by their high expression of CD44 and CD133, and this unique phenotype allows the identification of colorectal CSCs as a distinct population from the bulk tumor cells." (PMID 27738333, 2016). "Our findings that both IFDUC1 and TRIDUC1 ADSC lines had lower levels of the marker genes (CD105, CD73, CD90, CD44, CD106) when compared with NORMA1-4, supports a link with impaired tumor ADSC differentiation into osteogenic and chondrogenic lineages." (PMID 26968831, 2016). "CD44 and Hyaluronan Mediated Motility Receptor (RHAMM) are the two major cell surface proteins HA bind to trigger downstream signaling which promotes tumor growth and metastasis." (PMID 27595989, 2016). "HAPLN1 and the tumor progenitor cell markers CD44 and LGR5 were detected in tumor cells at the tumor-stroma interface and in cells arranged in an “Indian file” pattern." (PMID 27191501, 2016). "To explore the mechanism behind the antitumor activity of grifolin, we performed a screening of genes related to tumor adhesion/invasion regulation, including MMP1,2,3,9,19, TIMP-1,2,3, CD44, CDH1 and PCDH10." (PMID 27626695, 2016). "CSC-like cells were independently isolated from CRC cells using CD133, CD44 or EphB2-high as markers and the features of these cells as CSC-like cells were proven by tumor sphere formation assay." (PMID 27833077, 2016). "First, there appeared to be more double-stained CD44 and ALDH1 cells within a tumor than anticipated." (PMID 27768764, 2016). "MMP14 can cleave a variety of substrates, including cell surface proteins (such as CD44) and other MMPs (such as pro-MMP2 and pro-MMP13), and induce ECM degradation and tumor cell invasion by increasing the secretion of other MMPs." (PMID 27564100, 2016). "Our study is the first to show that the proportion of CD44+ and/or CD24+ cells increases in PDAC-derived cell lines compared with the corresponding tumor tissues." (PMID 27414409, 2016). "Overall, these findings suggest that grifolin decreased ROS generation and intracellular ATP to suppress tumor cell adhesion/migration via impeding the interplay between PGC1α and Fra-1 /LSF-MMP2/CD44 axes." (PMID 27626695, 2016). "CD44+CD24−/low, CD44+CD24−/lowESA+, CD133+, and ALDH1+ cancer cells are CSC candidates with high tumor-initiating and cancer formation abilities in vitro and in vivo." (PMID 27335684, 2016). "IHC confirmed that the expression patterns of the CSC markers were similar in the corresponding tumor tissues, although CD24 and CD44 expression levels were considerably lower." (PMID 27414409, 2016). "A novel tumor stem cell niche (CD133 and CD44), a specific cellular environment at the brain invasion border (TNC and MAP2) and a novel role for pituitary stem cells in the pathogenesis of adaCP has been proposed." (PMID 26927026, 2016). "In this study, our results show that CD74 and CD44 coordinately promote actin polymerization via RHOA-mediated CFL1 phosphorylation, enhancing tumor cell metastasis." (PMID 27626171, 2016). "CD44 has the capability to bind to its primary ligand hyaluronic acid (HA), which initiates CSC attachment to the extracellular matrix and contributes to tumour cell migration." (PMID 27825361, 2016).
tumor (continued). "Since the detection of metastatic tumour cells in the lymph nodes was difficult, serial sections were stained after a brief fixation, for GRPR and CD44 (an epithelial marker)." (PMID 27827443, 2016). "Inhibition of miR-141 increases both CD44+ and CK5+ cells by targeting Stat5a and progesterone receptor (PR), and enhances the abilities of mammosphere formation and tumor initiation." (PMID 26349457, 2016). "Several downstream target genes of WNT/β-catenin signaling, such as CD44, C-myc, MMP2, MMP7 and TIMP2, can affect tumor growth, proliferation, invasion and metastasis." (PMID 27835587, 2016). "CD44 knockdown (KD) depleted FGFR2 and other GCSC markers, decreased c-Myc and Sox2 expression, and suppressed tumor growth, whereas CD44 activation led to FGFR2 induction." (PMID 27107424, 2016). "The LNCaP-CRPC cells have also acquired some phenotypic CSC markers including CD44, α2β1, and ABCG2, all of which have been shown by us to enrich for tumor-initiating and tumor-propagating cells in different PCa models." (PMID 26871947, 2016). "When CD44+CD24low/− cells were injected into the fat pads of SCID mice, tumors formed rapidly, but CD44+/CD24−/low cells infected with Ad5/3-Δ24 showed slower tumor formation." (PMID 26980708, 2016). "The expression of Oct4, Sox2, Gli1, CD44, CD133, p-AKT, and p-ERK was positively correlated with a more aggressive tumor phenotype and poorer overall prognosis." (PMID 26769843, 2016). "This CD44+/CD133+ cell population is thought to initiate and sustain tumor growth, and thus is an obvious target for therapeutic treatment." (PMID 27738333, 2016). "The important aspect we have shown, for the first time, is that we can predict the three dimensional margins of the tumour based on GRPR expression, which is corroborated by CD44 staining." (PMID 27827443, 2016). "CD44 mediates the recruitment of active MMP-7 and HB-EGF precursor to form a complex on the surface of tumor cells." (PMID 27271600, 2016). "In breast cancer, overexpression of RANK drives EMT and expansion of the CD44+/CD24− CSC population, ultimately leading to increased tumor growth and a substantially higher number of metastases." (PMID 27058560, 2016). "Although more undifferentiated, and with tumor cells containing increased ALDH and CD44 expression, holospheres had superior ability to adhere to new substrates and to initiate cellular invasion." (PMID 26742076, 2016). "IHC staining of tumour tissues confirmed knockdown of SAE2 level and reduced levels of CSC markers (ALDH1A1 and CD44)." (PMID 27465491, 2016). "Studies have demonstrated that HA receptors, such as CD44 and RHAMM, are overexpressed in various types of tumor metastasis." (PMID 28335277, 2016). "In this study, we assessed the cooperative role of CD44 and FGFR2 in cross regulation and GC tumor initiation." (PMID 27107424, 2016). "The mechanism by which miR-373 contributes to tumor progression and metastasis has been attributed to its ability of binding to the 3′UTR of CD44 mRNA and repressing its translation." (PMID 27671416, 2016). "Although our study revealed the positive correlation between CSCs marker CD44 and tumor TNM stage and survival of patients with HCC, CD44 itself as a biomarker has its limitations on predicting prognosis and clinicopathological parameters in patients." (PMID 27330410, 2016). "As expected, we found that gene expression patterns are different in PC tumor samples compared to normal, undiseased peritoneum with a number of genes differentially regulated: BAG1, CCNB1, CD44, CLDN4 and 6, MMP2, MKI67, MUC1, MYBL2, and SERPINB3." (PMID 27542596, 2016). "These spheroid ovarian CSCs showed elevated levels of the CSC marker proteins CD44 and CD117, as well as increased Notch1 mRNA levels when compared to parental bulk tumor cells." (PMID 27626163, 2016).
tumor (continued). "While CD44+/CD24− BCSCs display a mesenchymal-like feature and are localized at the tumor invasive front, ALDH+ BCSCs are epithelial-like and are found at the centre of the tumor." (PMID 27759034, 2016). "In ADC, CD133, CD44, ALDH1 and Nanog were expressed in 46.9%, 33.6%, 47.3%, and 42.5% of tumor cells, respectively." (PMID 27285762, 2016). "In SqCC, CD44, ALDH1, SOX2 and Nanog were expressed in 88.0%, 73.2%, 71.1%, and 92.2% of tumor cells, respectively." (PMID 27285762, 2016). "Next, multicolor flow cytometry was used to evaluate the percentage of cells that were positive for CD24, CD44, EpCAM, CD133, and their combinations in three tumor-derived cell lines." (PMID 27414409, 2016). "We showed high expression of the examined CSC markers among all of the cell lines and tumor samples, with the exception of CD24 and CD44, which were enriched under in vitro conditions compared with tumor tissues." (PMID 27414409, 2016). "Behavioral observation further depicted the critical roles of CD44 and CD24 in maintaining the CSC characteristics such as resistance to therapy, self-renewal capacity, tumor initiation capacity, and metastatic potential in NPC CSCs." (PMID 27521216, 2016). "It is well known that downstream signaling prompted by CD44 and RHAMM on interaction with HA is crucial for HA mediated tumor growth and metastasis in various tumor types including bladder." (PMID 27595989, 2016). "The results of tumour growth curve and tumour weight showed that SALL4 knockdown significantly retarded the growth of xenograft tumours in mice; however, the simultaneous overexpression of CD44 greatly accelerated xenograft tumour growth." (PMID 27819668, 2016). "We showed that cancer stem cell markers (AlDH1A1, CD44) and the differentiation marker α-fetoprotein were upregulated in VX2 tumor cells." (PMID 26873175, 2016). "Compared with their respective tumor tissues, the cell lines were markedly enriched for CD24+ and CD44+ cells." (PMID 27414409, 2016). "Both CD44 and CD133 are known as putative markers for colorectal CSCs and CD133+ CD44+ tumor cell populations are responsible for liver metastasis." (PMID 27533463, 2016). "In our studies, we demonstrated that CCL2 gene silencing in MDA-MB-231 tumor xenografts inhibited ALDH1 expression, and reduced the number of CD24-/CD44+ cells." (PMID 27283985, 2016). "Limiting dilution tumor cell transplantation assays demonstrated that the bulk tumor cell population comprised ~0.01% BTIC, whereas the CD44+/CD24− fraction constituted ~1–2% BTIC." (PMID 27447971, 2016). "Analyses of CD44 and CD24 expression showed both cell lines had tumor-initiating CD44+/CD24low cell population, however transformed K5+/K19- cells had more proportion of these cells." (PMID 27941987, 2016). "Following TME Stimulation and sorting of CD44+/β1+ cells, a modest increase in tumor growth was observed when CD44+/β1+ cells were removed, suggesting that the remaining cells (Group 2) may have a slightly more aggressive phenotype than the CD44+/β1+ cells themselves (Figure 8A2)." (PMID 27835603, 2016). "MEC cells of IFDUC1, derived from a tumor characterized as ER+/PR+/Her2+ and non-BRCA1 hereditary were both CD44+ and CD24+." (PMID 26968831, 2016). "Before we evaluated the prognostic effects of the expression of CD133 and CD44 in PDX models, we first analyzed the tumor growth of different groups." (PMID 27329727, 2016). "This included EC-specific proteins (e.g. COL1A1, FBN1), tumour-specific proteins (e.g. ITGB1) and proteins up-regulated in both cell types (FN1, THSB1, CD44, ITGA4, CTGF)." (PMID 27049916, 2016). "We found that CD44 depletion leads to decrease of p-NF2 and p-NF2/NF2, indicating the activation the tumor suppressor function of NF2." (PMID 25605020, 2015). "CD44 was the first CSC marker described in a solid malignancy, and a high frequency of CD44 positive cells in HNSCC strongly correlates with recurrence and tumor aggressiveness." (PMID 26626427, 2015).
tumor (continued). "Our results demonstrate, for the first time, that targeting CD44 surface antigen after gemcitabine treatment in human-PDAC derived xenografts, is able to eliminate the remaining tumor cells in vivo." (PMID 26244163, 2015). "Detailed phenotypic and molecular profiling in Du145 and LAPC9 models shows that the CD44+, α2β1+, ABCG2+, and ALDH+ cell populations identify overlapping subsets of tumor-initiating cells." (PMID 26246472, 2015). "In this study, we analyzed the tumor metastasis related factors KAI1/CD82, CD44, MMP7 and β-catenin, to provide a new direction for investigating the metastasis and prognosis of CRC." (PMID 26408312, 2015). "To further address the correlation between CD24, CD44, and SSEA4 expression, we performed containing of these markers on residual tumor nodules after AC chemotherapy and on untreated tumors of three independent models." (PMID 26607327, 2015). "Whereas the tumor sizes from the mice immunized with PBS were bigger than that of mice immunized with the CD117+CD44+CSC (***p < 0.003); the time of tumor occurrence was also earlyer than that of mice immunized with the other vaccines (*p < 0.05)." (PMID 26497895, 2015). "Since CSCs were enriched in CD44+ and/or CD133+ cell population had been reported, H1299 cells from monolayer and tumor spheres were analyzed for CD44/CD133 double-staining by flow cytometry." (PMID 25669973, 2015). "The expression of KAI1/CD82, CD44, MMP7 and β-catenin is related to tumor metastasis and prognosis in CRC." (PMID 26408312, 2015). "We identified a subpopulation of CMC cells showing human breast CSC features, including expression of specific markers (i.e. CD44, CXCR4), growth as mammospheres, and tumor-initiation in mice." (PMID 25884842, 2015). "As seen in cancer stem cells isolated from tumor xenografts, the 12 T cells showed similar enrichment of surface markers CD24/CD44/ESA and CD133." (PMID 26597727, 2015). "We demonstrated that CD44 was partially expressed both in primary NPC tumor sections and in secondary tumor sections, suggesting that NPCs contain CSCs." (PMID 26202311, 2015). "We found that hypoxia expands different breast stem/progenitor cell populations (cells with increased aldehyde dehydrogenase activity (Aldefluor+), high mammosphere formation capacity and CD44+CD24−/low cells) both in primary normal epithelial and tumor cells." (PMID 26372732, 2015). "We found that CD44 depletion leads to decrease of p-NF2 and p-NF2/NF2, indicating the activation of the tumor suppressor function of NF2." (PMID 25605020, 2015). "We observed a significant inter-tumoral heterogeneity in the baseline expression of CD44 and CD24, and the distribution was normal between tumours from taxane-treated and taxane-naive patients." (PMID 25669750, 2015). "Su and colleagues have demonstrated that CD44 overexpression was induced by the Src kinase activity in malignant peripheral nerve sheath tumour (MPNST) cells, and that it contributed to tumour invasiveness." (PMID 25999819, 2015). "Serial tumor transplantation experiments have established that the Du145 ALDH+, and LAPC9 CD44+, CD44+α2β1+, and SP populations all can self-renew in vivo, attesting to their true CSC properties." (PMID 26246472, 2015). "Although no marker can be used universally to identify cancer stem cells, CD44 and CD24 are used extensively as potential surface markers with which to identify and isolate tumor initiating cells (cancer stem cells) in different cancers." (PMID 25605020, 2015). "The results suggest that CD44, CD47 and c-met participate in the development of the malignant biological behavior of OCCC and promote tumor progression and poor prognosis." (PMID 25658794, 2015). "We found that CD44+/ESA+, CD44+/CD24+ cells have a significantly higher possibility for colony and tumor sphere formation than CD44−/ESA− and CD44−/CD24− cells." (PMID 25849939, 2015).